Y_RNA (Y RNA )
Gene: Miscellaneous RNA gene on chromosome 1 (26,593,940 to 26,594,041, reverse strand). Ensembl gene ENSG00000252802.
Homologues: Orthologues: chimpanzee Y_RNA (100% identical), macaque Y_RNA (93% identical), pig Y_RNA (91% identical), dog Y_RNA (89% identical). Paralogues in human: RNY3 (94% identical), Y_RNA (94% identical), Y_RNA (93% identical), RNY3P1 (92% identical), Y_RNA (92% identical), Y_RNA (91% identical), Y_RNA (90% identical), Y_RNA (89% identical), Y_RNA (88% identical), RNY3P16 (87% identical), Y_RNA (87% identical), RNY3P11 (86% identical), and 99 more.